MMP9 (matrix metallopeptidase 9)
Description:
Matrix metalloproteinase that plays an essential role in local proteolysis of the extracellular matrix and in leukocyte migration. Could play a role in bone osteoclastic resorption (By similarity). Cleaves KiSS1 at a Gly-|-Leu bond. Cleaves NINJ1 to generate the Secreted ninjurin-1 form. Cleaves type IV and type V collagen into large C-terminal three quarter fragments and shorter N-terminal one quarter fragments. Degrades fibronectin but not laminin or Pz-peptide.
Synonyms: MMP-9; GELB; CLG4B; MANDP2
Tractability: Small molecule: a drug acting on it is in phase 2 or 3 trials; a structure with a bound ligand is known; a high-quality ligand is known; it has a high-quality binding pocket; it belongs to a druggable protein family. Antibody: a drug acting on it is in phase 2 or 3 trials; UniProt places it where antibodies can reach, with high confidence; its Gene Ontology location is reachable by antibodies, with high confidence; UniProt predicts a signal peptide or a membrane-spanning region. PROTAC: its protein half-life has been measured; a small molecule that binds it is known.
Target class: Metallo protease; Metallo protease M10A subfamily; Metallo protease MAM clan; Protease; Enzyme
Gene: Protein-coding gene on chromosome 20 (46,008,908 to 46,016,561, forward strand). Ensembl gene ENSG00000100985.
Subcellular location: Secreted, extracellular space, extracellular matrix
Subcellular location (Human Protein Atlas): Cytosol; Predicted to be secreted
Pathways (Reactome):
Extracellular matrix organization: Activation of Matrix Metalloproteinases; Assembly of collagen fibrils and other multimeric structures; Collagen degradation; Degradation of the extracellular matrix
Immune System: Interleukin-4 and Interleukin-13 signaling; Neutrophil degranulation
Signal Transduction: Extra-nuclear estrogen signaling; Signaling by SCF-KIT
Developmental Biology: EPH-ephrin mediated repulsion of cells
Disease: Dengue Virus-Host Interactions
Gene Ontology:
Molecular function: endopeptidase activity; identical protein binding; metalloendopeptidase activity; metallopeptidase activity; peptidase activity; protein binding; serine-type endopeptidase activity; collagen binding; zinc ion binding
Biological process: cell migration; cellular response to UV-A; collagen catabolic process; endodermal cell differentiation; extracellular matrix disassembly; negative regulation of apoptotic process; negative regulation of cation transmembrane transport; negative regulation of intrinsic apoptotic signaling pathway; positive regulation of DNA binding; positive regulation of epidermal growth factor receptor signaling pathway; positive regulation of keratinocyte migration; positive regulation of protein phosphorylation; positive regulation of release of cytochrome c from mitochondria; positive regulation of vascular associated smooth muscle cell proliferation; proteolysis; cellular response to lipopolysaccharide; ephrin receptor signaling pathway; extracellular matrix organization; macrophage differentiation; negative regulation of epithelial cell differentiation involved in kidney development; regulation of neuroinflammatory response; response to amyloid-beta; regulation of multicellular organismal process
Cellular component: extracellular exosome; extracellular matrix; extracellular region; ficolin-1-rich granule lumen; tertiary granule lumen
Genetic constraint (gnomAD): Loss-of-function variants: 73 observed, 73.42 expected, observed/expected ratio (o/e) 0.99, 90% interval 0.82 to 1.21. The upper end of that interval is the gene's LOEUF score, 1.21, which puts it in group 5 of 6, group 1 being the genes least tolerant of losing a copy. Missense variants: 943 observed, 971.35 expected, observed/expected ratio (o/e) 0.97, 90% interval 0.92 to 1.02. Synonymous variants: 412 observed, 399.46 expected, observed/expected ratio (o/e) 1.03, 90% interval 0.95 to 1.12.
Homologues: Orthologues: chimpanzee MMP9 (98% identical), macaque MMP9 (94% identical), rabbit MMP9 (83% identical), pig MMP9 (82% identical), dog MMP9 (81% identical), guinea pig MMP9 (80% identical), rat Mmp9 (75% identical), mouse Mmp9 (74% identical), zebrafish mmp9 (57% identical), tropical clawed frog mmp9 (56% identical), Caenorhabditis elegans zmp-3 (17% identical), Caenorhabditis elegans zmp-4 (15% identical), and 3 more. Paralogues in human: MMP2 (44% identical), MMP3 (26% identical), MMP13 (26% identical), MMP10 (26% identical), MMP14 (23% identical), MMP27 (23% identical), MMP1 (23% identical), MMP15 (23% identical), MMP16 (23% identical), MMP24 (23% identical), MMP25 (23% identical), MMP8 (22% identical), and 11 more.
Diseases named in the same sentence as MMP9 in open-access papers:
MMP9 is named in the same sentence as 1,261 diseases in open-access papers, as found by Europe PMC text mining. Sharing a sentence is not in itself a finding about the gene and the disease. The quoted sentences say what the papers report.
breast carcinoma (1,459 papers, 2001 to 2026). "Particularly, MMP-14 and MMP-9 have been linked to the migration, angiogenesis, and metastasis of breast cancer cells." (PMID 40867236, 2025). "On the other hand, our study suggests that MMP9 rs3787268 shows a protective effect on breast cancer susceptibility in three genetic models, including the additive model 1, the additive model 2, and the dominant model." (PMID 40735254, 2025). "While both have been established in breast cancer patients, increased MMP-9 levels are associated with a poor prognosis, while increased MMP-2 levels are linked to prolonged survival time." (PMID 41322296, 2025). "Increased MMP2/MMP9 levels in the blood were associated with a considerably reduced chance of survival for females with breast cancer." (PMID 40735254, 2025). "This study evaluated the relationship between MMP2 (rs2285053) and MMP9 (rs3787268) gene polymorphisms and the susceptibility to breast cancer in Bangladeshi breast cancer patients." (PMID 40735254, 2025). "Specifically, high pre-operative sera MMP-9 levels have been associated with increased relapse rates in breast carcinoma and decreased OS in various solid malignancies." (PMID 41573658, 2025). "The overexpression of MMP9 was associated with poor prognosis of patients diagnosed with oral or breast cancer." (PMID 40839565, 2025). "It has been shown that polymorphism in MMP9 were associated with breast cancer risk and chronic venous disease." (PMID 38166679, 2024). "Elevated levels of specific MMPs, such as gelatinases MMP-2 and MMP-9, have been found in breast cancer tissues and are associated with a more aggressive tumor phenotype." (PMID 38675538, 2024). "MMP-2 and MMP-9 are associated with tumor growth, invasion, angiogenesis, and inflammation in breast cancer." (PMID 38774755, 2024). "We then consolidated an OPN pathway and upregulated gene signatures from our findings (Spp1, Timp3, Col11a1, Mmp9, Mmp2, Fn1, Cd44, and Il-4) to interrogate how their predicted activity is associated with relapse-free survival in breast cancer patients." (PMID 39448577, 2024). "It has also been described that overexpression of MMP-2 and MMP-9 is associated with poor prognosis in breast cancer patients by promoting the invasive process due to their role in the degradation of ECM proteins." (PMID 38737746, 2024). "In vitro experiments using MDA-MB-231 breast cancer cells showed that omeprazole decreased the expression of two genes associated with promoting metastasis, namely, matrix metalloproteinase-9 (MMP-9) and C-X-C chemokine receptor 4 (CXCR4)." (PMID 38518996, 2024). "Overexpression of LCN2 in MCF-7 and HER2-positive breast cancer cells is associated with increased levels of MMP-9, enhanced stabilization and activation of its enzymatic activity, and protection from degradation." (PMID 39188682, 2024). "MMP9 expression has been consistently associated with tumor growth and metastasis and has been considered a potential therapeutic target in breast cancer." (PMID 39373616, 2024). "Our study not only sheds light on the regulatory mechanisms underlying MMP-9 expression in breast cancer but also opens new paths for the development of targeted therapeutic strategies." (PMID 39351229, 2024). "In particular, the protease MMP-9 is overexpressed in breast cancer and its expression is associated with a higher incidence of metastasis, and therefore it is used as a prognosis marker." (PMID 38405665, 2024). "The compelling association of MMP-9 with tumor invasiveness and poor prognostic outcomes has long underscored its significance in breast cancer." (PMID 39351229, 2024). "Overexpression of MMP-2 and MMP-9 was linked to poor prognosis in oral cancer, lung cancer, breast cancer, retinoblastoma, bladder cancer, and ovarian epithelial cancer." (PMID 38069361, 2023).
breast carcinoma (continued). "Comparative studies indicate that an escalated urinary MMP9 level corresponds to a fivefold risk of atypical hyperplasia and a more than thirteenfold risk of lobular carcinoma in situ (LCIS) compared to normal controls." (PMID 38250812, 2023). "Loss of CRP2 in breast cancer cells significantly decreases invadopodia formation, MMP-9 secretion, ECM degradation, and invasion in vitro." (PMID 37266453, 2023). "The upregulation of a set of MMPs, including MMP1, MMP2, and MMP9, has been associated with worse prognosis in different malignancies including breast cancer." (PMID 38017545, 2023). "Another downstream target of NF-κB is MMP9, which has a particular binding site for NF-κB on its promoter and is directly associated with the invasiveness of breast cancer." (PMID 36687217, 2023). "MMP-2 and MMP-9 play an important role in metastasis and have been linked to lymph node metastasis in breast cancer cell lines as well as to poor response to chemotherapy in osteosarcoma." (PMID 36674555, 2023). "Taken together, these findings suggest that AG prevents breast cancer by modulating estradiol metabolism and suppressing the expressions of MMP9 and proteins associated with angiogenesis." (PMID 37920216, 2023). "In a 2008 study conducted on 60 breast cancer patients, high serum levels of both MMP-9 and TIMP-1 were also associated with lower progression-free and OS rates." (PMID 35818030, 2022). "A meta-analysis comprised of 41 studies and 6517 breast cancer patients demonstrated that a higher expression of Mmp2 and Mmp9 in tumor cells of patients was strongly associated with larger tumors and metastasis to lymph nodes and distant organs." (PMID 36612044, 2022). "The lower possibility for HER2-positive breast cancer was associated with the presence of the MMP9 rs3918242 C allele." (PMID 36009438, 2022). "In breast cancer, a high expression of Osteopontin was associated with frequent osteolysis, inducing the expression of bone-resorbing proteases, cathepsin K, and MMP9." (PMID 36499741, 2022). "MMPs are strongly linked to breast cancer, and MMP-9 is the most often upregulated protein in breast cancer." (PMID 35164236, 2022). "Higher expression of Mmp2 and Mmp9 was also associated with histological grade, higher clinical stage, and predicted poor survival of breast cancer patients." (PMID 36612044, 2022). "In another study, gene transfer of MMP-9 to ex vivo breast cancer tumors caused tumor regression via increased neutrophil infiltration and an activation of tumor-associated macrophages (TAMs)." (PMID 36497286, 2022). "Of note, the overexpression of HDAC1, HDAC6, or HDAC8, in breast cancer cell lines, was shown to be associated with increasing cell invasion and matrix metallopeptidase 9, which is a protein-coding gene known as MMP9." (PMID 35764927, 2022). "Higher MMP9 expression is associated with a poorer prognosis for patients with breast cancer or colorectal cancer." (PMID 35910372, 2022). "Panel A including MMP-9/TIMP-1 in early stages demonstrated a higher diagnostic value for breast cancer than the rest of the panels." (PMID 35222743, 2022). "This study also linked MMP-9 overexpression to high-grade breast cancers such as triple-negative breast cancer and HER2-positive breast cancer subtypes, which are also related to relapses and lymph node metastases." (PMID 35586209, 2022). "The role of MMP9 in metastasis has been reported to be diverse, but its up-regulation is associated with poor survival, e.g., in breast cancer patients." (PMID 36361816, 2022). "The role of LCN2 in cancer metastasis is further confirmed by the fact that its deficiency in murine breast cancer cells had resulted into a significant reduction in the size and metastasis of the primary tumors with a reduced MMP9 levels in blood." (PMID 34588926, 2021). "In the case of breast cancer, the association between MMP-9 and the migration potential and invasiveness of cells has been demonstrated." (PMID 34884588, 2021).
breast carcinoma (continued). "Other studies have shown increases of breast cancer cell invasion and migration as well as metastasis associated with higher MMP-9 activity caused by miR-182 regulation." (PMID 34445715, 2021). "The obtained results suggest that CP causes a decrease in the survival of breast cancer cells of various invasiveness, and the downregulation of MMP-9 enhances this effect, mainly by inducing apoptosis." (PMID 34884588, 2021). "The role of MMP9 in activating and proliferating breast cancer cells through collagen digestion and association with tumor-suppressive genes has been indicated in studies." (PMID 34307654, 2021). "While MMP-9 has been associated with the metastatic cascade in breast cancer setting and the Axl signaling pathway, our study demonstrated that MMP-9 secretion increased in the shAXL Raw264.7 cells." (PMID 33791875, 2021). "Previous studies have shown that higher expression of CD147, MMP-2, and MMP-9 is associated with breast cancer progression." (PMID 34096887, 2021). "In ER+ breast cancer, MMP-9 secreted by TAMs was associated with worse overall survival, but not in ER-negative breast cancer or triple-negative breast cancer (TNBC)." (PMID 34717710, 2021). "This study aimed to determine the relationship between rs17576 (MMP-9) polymorphism and increased cancer risk in a Brazilian breast cancer cohort." (PMID 33146350, 2020). "Nevertheless, there is strong evidence of an association between MMP expression and breast cancer invasion and metastasis in patients, including MMP9." (PMID 31910058, 2020). "This builds upon observations that MMP9 digestion of laminin-111 drives a loss of cell polarity and tumor growth in primary breast cancer models." (PMID 33014869, 2020). "The expression of Kiss1 in human breast cancer specimens inversely correlates with levels of matrix metalloproteinase-9 (MMP-9) and IL-8—genes implicated in metastatic invasion." (PMID 33096815, 2020). "In summary, the results of this study show a significant association between MMP-9 rs17576 (GG) genotype and breast cancer risk." (PMID 33146350, 2020). "MMP-9 degrades protein in extracellular matrix and it is associated with tumor invasion, metastasis, and poor prognosis in breast cancer." (PMID 32458624, 2020). "In this study, the MMP-9 rs17576 GG polymorphic variant was shown to be significantly associated with breast cancer risk in premenopausal women, while the AG and GG genotypes were associated with increased cancer risk in postmenopausal women." (PMID 33146350, 2020). "Previous authors have reported that MMP-2 was regulated via PI3K and NF-kB pathway in breast cancer and the inhibition of MMP-9 was associated with the inhibition of p-JNK." (PMID 33042020, 2020). "In this study, we evaluated the association between MMP-9 rs17576 polymorphisms and breast cancer risk in a Brazilian cohort." (PMID 33146350, 2020). "Several proteins overexpressed in bone-seeking breast cancer cells were associated with increased migration and invasiveness in bone metastasis, including Osteoactvin, Cadherin-11, MMP-9 and CXCR4." (PMID 32226538, 2020). "Additional studies have found that a subset of the MMPs (e.g., MMP-2 and MMP-9) are upregulated in breast cancers and are associated with poor outcomes." (PMID 32384738, 2020). "One of miR-143 target molecule is MMP-9 that is associated with tumor invasion, metastasis, and poor prognosis of breast cancer via protein degradation in extracellular matrix." (PMID 32458624, 2020). "Several studies have observed high levels of LCN2 associated with MMP-9 as a heterodimer in the urine of breast cancer patients, in high-grade endometrial cancer tissues, and in cell lysates of oral squamous carcinoma cell lines." (PMID 32575507, 2020). "HRPAP20 (hormone-regulated proliferation-associated protein 20) is a CaM-binding proliferation-associated protein highly expressed in invasive breast cancer cells and is implicated in matrix metalloprotease-9 (MMP-9) secretion." (PMID 31991573, 2020).